IL1B (interleukin 1 beta)
Diseases named in the same sentence as IL1B in open-access papers (continued):
Sharing a sentence is not in itself a finding about the gene and the disease.
tumor (continued). "The influence of NF-κB extends beyond tumor cells: in cancer-associated fibroblasts (CAFs), radiation induces secretion of pro-inflammatory cytokines (e.g., IL-6, IL-1β, TNF-α) in an NF-κB-dependent manner, creating a supportive niche for tumor cell survival." (PMID 40725389, 2025). "The elevated expression of several cytokines such as IL-1β, IL-6, IL-10, TNF-α, and TGF-β has been reported to be involved in tumor initiation and progression in various types of cancer." (PMID 40722593, 2025). "This target-selective phagocytic activity was associated with increased secretion of pro-inflammatory cytokines (IL-6, IL-1β, TNF-α, IL-12) following co-culture with tumor cells." (PMID 41388305, 2025). "CAR-T therapy combined with Thalidomide limits IL-1β-related toxic side effects of CAR-T treatment and improves the anti-tumor effect of CAR-T therapy." (PMID 40002808, 2025). "For instance, α4β1 integrin on myeloid-derived suppressor cells (MDSCs) binds tumor-derived molecules like IL-1β and SDF-1α, promoting MDSC accumulation within tumor tissues and suppressing T cell function." (PMID 41451227, 2025). "Subsequently, many intracellular components, including IL-1β, HMGB1, and tumor antigens, were rapidly released." (PMID 40698137, 2025). "Programmed cell death processes in tumor cells are also triggered in response to other inflammatory cytokines such as TNF, IL-1β, MCP-1 (monocyte chemotactic protein 1), and others." (PMID 40821768, 2025). "In OSCC, tumor-derived IL-1β can act in a paracrine manner to promote ECM degradation and tumor cell invasion." (PMID 41044643, 2025). "The mechanism by which M2-like TAMs induce EMT involves the secretion of various soluble factors, including IL-1β, transforming growth factor β, and IL-8, which are potent inducers of EMT and contribute to tumor cell invasion and migration." (PMID 39983469, 2025). "M1-type TAMs secrete factors that exert anti-tumor effects: IL-12, TNF-α, and IL-1β activate cytotoxic T cells and NK cells, and CXCL9 recruits Th1 cells and cytotoxic T cells to the TME, enhancing anti-tumor immunity." (PMID 40375990, 2025). "P.g. and F.n. upregulate IL-1β mRNA/protein via AIM2 and NLRP3 inflammasome dysregulation in an OSCC cell line, promoting a pro-tumor inflammatory phenotype." (PMID 40924302, 2025). "In GBM in particular, macrophage-derived IL-1β promotes edema, induces GBM tumor growth, promotes cancer stem cell phenotype, and leads to further immune reprogramming by GBM cells including macrophage polarization and recruitment." (PMID 41445746, 2025). "Antigen pulsing was performed by culturing the mDCs in the presence of cytokines rh-IL-4, rh-GMC-SF, rh-IL-6, rh-IL1b, rh-IL12, rh-IL-15, and rh-TNF-α and incubating 106 cells with 18 μg of tumor lysate or cultured cell lysate for 18 h." (PMID 40733726, 2025). "In mouse models, antagonising IL-1β or IL-1R1 reduces TAM infiltration and inhibits tumour angiogenesis, significantly prolonging survival." (PMID 40630800, 2025). "TMAO can induce gasdermin E (GSDME)-mediated tumor cell pyroptosis by activating the endoplasmic reticulum kinase PERK, leading to release inflammatory factors such as IL-1β and IL-18 into the tumor microenvironment." (PMID 40241220, 2025). "Responders exhibited elevated expression of IL1B, CXCL5, HMGB1, and IFNGR2, indicative of an inflamed tumor microenvironment and type I/II interferon signaling." (PMID 40723289, 2025). "The tumor microenvironment in PC is characterized by chronic inflammation with overproduction of cytokines such as IL-6, TNF-α, and IL-1β." (PMID 41514529, 2025). "In TNBC, IL-1β promotes TAM recruitment, immunosuppression, and tumor progression, highlighting its relevance as a therapeutic target." (PMID 40868199, 2025). "Pro-inflammatory cytokines such as interleukin (IL)-6, IL-1β, IL-8, and tumor necrosis factor-alpha (TNF-α) are frequently upregulated and contribute to tumor cell proliferation, migration, and invasion." (PMID 40612845, 2025).
tumor (continued). "This increased IL-1β then promotes the production of APC progenitors, thereby enhancing the immune response to tumor antigens and boosting tumor-antigen-specific T cell activation." (PMID 40159726, 2025). "Biological evidence highlights the involvement of pro-inflammatory cytokines (IL-6, IL-1β, TNF-α), NF-κB signaling, and activation of the tryptophan–kynurenine pathway (IDO), suggesting a link between tumor-related processes and mood alterations." (PMID 41514529, 2025). "Specifically, inflammasomes release IL-1β and IL-18, activating NF-κB and hypoxia-inducible factor 1-alpha (HIF-1α) signalling in the tumour microenvironment." (PMID 41148809, 2025). "A live attenuated version of the ZIKV vaccine has been shown to enter GBM tumor cells via αvβ5 and/or Ax1 receptors, which in turn induce apoptosis (caspase-3) and pyroptosis (GSDMD/IL-1β)." (PMID 41291696, 2025). "In early tumor stages, M1 macrophages exert anti-tumor effects through pro-inflammatory cytokine production, such as TNF-α and IL-1β, and antigen presentation, yet their functions are often compromised by immunosuppressive mechanisms within the TME." (PMID 41459510, 2025). "These reprogrammed astrocytes secrete IL-6 and IL-1β, activating JAK2/STAT3 signaling in tumor cells and enabling dynamic switching between dormancy and proliferation within the CNS niche." (PMID 41562063, 2025). "Tumor cells and surrounding immune cells release cytokines such as tumor necrosis factor-alpha (TNF-α), interleukin-6 (IL-6), and interleukin-1β (IL-1β)." (PMID 41180630, 2025). "In the breast cancer tumor-bearing animals, PVSO reduced tumor growth, and suppressed serum and hypothalamic inflammatory cytokines (TNF-α, IL-1β, and IL-6) and NF-κB signaling." (PMID 40993108, 2025). "The tumor-only group also significantly increased IL-6 and TBAR levels in the plasma, as well as the IL-1β mRNA level in the gastrocnemius, compared to the control group (p < 0.001)." (PMID 40136406, 2025). "We performed a correlation analysis between the levels of TNF-α and IL-1β expression in macrophages and UPP1 levels in tumor cells." (PMID 41243973, 2025). "This analysis highlighted the consistent induction of pro-inflammatory cytokines such as IL-1β, IL-6, IL-8, IL-10, IL-17A/F, and TNF, which are known to play central roles in immune activation, macrophage polarization, and tumor–immune cell crosstalk." (PMID 41514627, 2025). "IgE binding to its receptors induces tumor-associated macrophages (TAMs) and monocytes to secrete high levels of cytokines, such as TNF-α, IL-1β, and MCP-1, which enhance ADCC against tumor cells." (PMID 41567205, 2025). "In vitro coculture experiments have demonstrated that LSECs and metastatic tumor cells interact via ICAM‐1/LFA‐1, promoting the release of tumor‐derived PGE‐2, IL‐6, VEGF, and MMPs, as well as LSEC‐derived IL‐1β, IL‐6, and TNF‐α into the TME." (PMID 40027151, 2025). "One of the principal explanations for such observations is the fact that α‐SMA is a marker for CAFs which arise from normal fibroblasts via TGF‐β, osteopontin (OPN), interleukin‐1β (IL‐1β), PDGF, TNF‐α, and FGF signals from the tumor." (PMID 39245631, 2025). "In vivo efficacy was evaluated in AOM/DSS-induced CRC mice, monitoring tumor growth, inflammatory markers (TNF-α, IL-1β, IL-6, MPO), and gut microbiota composition." (PMID 40733148, 2025). "The production of IL‐1β and caspase‐1 after NLRP3 activation in TAMs contributes to the formation of an inflammatory tumor microenvironment, which facilitates tumor metastasis." (PMID 40671401, 2025). "Accordingly, these cells produce high levels of pro-inflammatory cytokines, such as TNF, IL-1β, IL-6, IL-12, IL-23, and CCL2, to promote immune responses against bacteria, intracellular pathogens, and tumor cells." (PMID 40109347, 2025). "This activation leads to an increased expression of various inflammatory cytokines within the tumor microenvironment, including TNF-α, IL-6, IL-1β, and other cytokines." (PMID 40487290, 2025).
tumor (continued). "ATP released from dying cancer cells activate P2X7 receptors on DCs leading to activation of the NLRP3 inflammasome, IL-1β release and priming of IFN-γ-producing tumor antigen-specific CD8+ T cells." (PMID 39995666, 2025). "IL-1β activates a cascade of inflammatory mediators, fostering a protumoral TME and facilitating tumor progression." (PMID 40940992, 2025). "Dying tumor cells treated with chemotherapy release ATP, which activates the NLRP3 inflammasome and IL-1β–IL-1 receptor (IL-1R) signaling in dendritic cells, driving an effective CD8 T-cell response against transplantable tumor cells." (PMID 40718836, 2025). "Inflammatory cytokines in TME, such as IFN-ꝩ, IL-1β, IL-6, and TNF, further favorize cancer immune escape by augmenting PD-L1/PD-L2 expression on tumor cells including TNBC." (PMID 40940764, 2025). "An experimental study reported that IL-1β secreted by M2-like TAMs induces the expression of CD26 in MPM cells, which contributes to the enhancement of the tumor's self-renewal capacity and sphere formation ability." (PMID 39983469, 2025). "Pro-inflammatory cytokines such as IL-1β, IL-6, and TNF-α not only drive tumor progression and invasion but also contribute to chemotherapy resistance, underscoring their relevance as both biomarkers and therapeutic targets." (PMID 41155372, 2025). "The tumour-biased CXCL8hi_IL1Bhi_Mac macrophages secreted proinflammatory and tumour-supporting cytokines like CXCL8, IL1B, and CCL3, inducing cancer cell growth, invasion, and metastasis." (PMID 41312167, 2025). "Consistent results were achieved for all 94 paired tumour–normal samples for TNF-α and IFN-γ, for 93 paired samples for TGF-β1 and IL-1α, for 90 paired samples for IL-1β and IL-12, and for 87 paired samples for IL-2 and IL-6 expression." (PMID 41465261, 2025). "IL1RAP expression has been identified on the tumor and stromal cells of multiple tumors, promoting an immunosuppressive microenvironment, and its interaction with IL1A/IL1B has also been specifically targeted in a phase 1b clinical trial." (PMID 40647416, 2025). "The types of DAMPs from the damaged tumor cells after RT include calreticulin (CALR), adenosine triphosphate (ATP), type I interferon (IFN), heat shock proteins (HSPs), S100 proteins, and interleukin-1 beta (IL-1β)." (PMID 40895459, 2025). "Further analysis showed increased production of proinflammatory interleukins such as IL‐1β and IL‐16 and accumulation of various chemotactic agents, including CCL3, CCL4, CCL5, CXCL9, CXCL10, and CXCL11, in the tumor tissue." (PMID 41221154, 2025). "This inflammatory state promotes the release of cytokines (e.g., IL-1β, IL-6, IL-10, IL-18, TNF-α) and growth factors that facilitate tumor cell proliferation, invasion, and angiogenesis, while simultaneously impairing immune surveillance." (PMID 41114747, 2025). "Concurrently, we observed marked upregulation of multiple pro-tumor factors, including MMP-11, IL-6, IL-1β, CCL5, and CCL2." (PMID 41276817, 2025). "Our previous studies demonstrated a significant increase in TNF-α, IL-6, IL-18, IL-1β, and INF-γ in the skeletal muscle of tumor-bearing animals, which normalized after treatment with withaferin A (WFA)." (PMID 39996717, 2025). "IL-1β and TNF-α play crucial roles in modulating the tumor microenvironment and promoting tumor progression." (PMID 41243973, 2025). "After IL-1β-mediated activation of the cyclooxygenase 2 pathway, the microRNA (miRNA) tumor suppressor miR-101 was dramatically reduced in NSCLC cells, suggesting a potential role for IL-1β in LC progression." (PMID 41179937, 2025). "These macrophages, in turn, secrete IL-1β, which upregulates LCN2 expression in tumor cells, establishing a paracrine feedback loop." (PMID 41436606, 2025).
tumor (continued). "Furthermore, the relationship between M1-like macrophages and tumor metastasis may be partially attributed to the influence of inflammatory cytokines, such as IL-1β, TNF-α, and IL-6, which can directly or indirectly promote the proliferation of endothelial cells." (PMID 40438141, 2025). "In AOM/DSS-induced CRC mice, KGM-CUR/PSM microspheres significantly improved survival and inhibited CRC tumor growth, and effectively reduced the expression of inflammatory cytokines (TNF-α, IL-1β, IL-6) and myeloperoxidase (MPO)." (PMID 40733148, 2025). "The development into M1 macrophages leads to increased production of pro-inflammatory cytokines (IL1-β, TNF-α, and IL-6), and support of the adaptive anti-tumor activity." (PMID 41440002, 2025). "For example, pro-inflammatory cytokines in the tumor microenvironment (e.g., IL-6, TNF-α, and IL-1β) can activate signaling pathways (e.g., NF-κB and STAT3) that promote tumor cell proliferation, invasive capacity, and resistance to therapy." (PMID 39940440, 2025). "However, a comparative study assessing NLRP3 (NOD-like receptor protein 3), caspase-1, IL-1β, and IL-18 mRNA and protein expression in hen and human OvCa found increased protein expression of caspase-1, IL-1β, and IL-18 in surface epithelium, tumor cells, and immune cells." (PMID 40718836, 2025). "Conversely, higher FSS suppressed tumor cell motility, possibly by stimulating macrophage secretion of cytotoxic or anti-migratory mediators such as TNF-α, IL-1β, or reactive species." (PMID 41439943, 2025). "For example, OLT117 has been shown to disrupt the IL-1β/IL-6/STAT3 axis in the TME, which decreases the immunosuppressive activity of MDSCs and improves anti-tumor immunity when combined with anti-PD-1 therapy." (PMID 40141358, 2025). "This study aimed to explore the relationship between the presence of F. nucleatum and the expression of inflammation-related genes (IL6, IL1B, IL10, IL17, TNF) in tumor and matched normal tissue of Kazakhstani CRC patients." (PMID 41267807, 2025). "By analysing IL1β, IL10, IL18, TNF-α, TLR4, GATA3, and CD68 expression in 50% of PCa HHV-infected FFPE with an elevated inflammation index (61.8%/21), we detected hyper-expressed levels of IL1β, IL18, and TNF-α in the tumour microenvironment." (PMID 40430084, 2025). "The critical breakthrough occurs when inflammatory cytokines (TNF-α, IL-1β) increase tumor cell MHC-I expression and enhance antigen processing machinery, making previously cryptic tumor epitopes available for cross-presentation." (PMID 41012173, 2025). "On the other hand, though very few co-stimulatory and checkpoint interactions were present in the KPC-3403 tumor at baseline, these interactions were restored to a similar pattern compared to that of the KPC-4545 model following anti-IL-1β treatment." (PMID 39948655, 2025). "KYNA alters the tumor microenvironment, boosting immunosuppressive neutrophils and inducing CD8+ T cell exhaustion, undermining PD-L1 and IL-1β blockade therapies." (PMID 40413543, 2025). "IL-6 enhances immune cell recruitment and promotes tumor progression by inducing epithelial-to-mesenchymal transition (EMT) and angiogenesis, while IL-1β and IL-18 are key pro-inflammatory cytokines activated by the NLRP3 inflammasome pathway." (PMID 40218944, 2025). "Key cytokines of interest include IL-6, TNF-α, IL-1β (as prototypical pro-tumor inflammatory cytokines), as well as others such as IL-8 (CXCL8), IL-10, and IL-17, which together shape the tumor immune microenvironment." (PMID 41007766, 2025). "Other studies have shown that IL-1β can promote MDSC accumulation, thereby driving tumor progression." (PMID 40429988, 2025). "In MMRd tumors, resistance following anti-PD-1 treatment is driven by the expression of TIM3, LAG3, CTLA4, and TIGIT by TILs, as well as tumor clonal selection and the expression of TREM2, CSF1R, IFITM, TMEM176B and IL1B by myeloid cells." (PMID 40027748, 2025).
tumor (continued). "IL-1β stimulates endothelial cells to secrete vascular endothelial growth factor (VEGF), a key factor that promotes angiogenesis and facilitates tumor progression." (PMID 40453286, 2025). "Taken together, while anti-IL-1β treatment appears to enhance the CAF and immune cell infiltration in the KPC tumor with lung metastasis potential, it appears to suppress the function of CAF and immune cells in the KPC tumor with liver metastasis potential." (PMID 39948655, 2025). "NF-κB signaling is triggered in macrophages by tumor-derived cytokines such as TNF-α and IL-1β, further enhancing the production of IL-6 and IL-10, that further promote tissue remodeling and angiogenesis." (PMID 40160820, 2025). "M2-like TAMs are key sources of IL-1β via inflammasome (particularly NLRP3) activation, supporting tumor progression through enhanced angiogenesis, immune evasion, and chronic inflammation." (PMID 40868199, 2025). "As already elaborated, tumor-cell-derived CCL3 activates the MAPK pathway, leading to the production of IL-1β, IL-6 and TNF-α." (PMID 41153795, 2025). "This dual activation/suppression pattern suggests evolved immune evasion through macrophage-driven chronic inflammation (IL-6/IL-1β axis) and PD-1/STAT1-mediated TIL exhaustion, while compromised antiviral responses facilitate tumor immunoediting." (PMID 40697520, 2025). "The deacetylation of BMAL1 by lactate/interleukin-1 beta (IL-1β) amplifies LDHA expression and tumor growth." (PMID 40725147, 2025). "In the colon, LPS and other pathogen-associated molecules activate mucosal immune cells to release pro-inflammatory cytokines (e.g., IL-1β, IL-6, TNF-α), creating an environment conducive to tumor promotion." (PMID 41374093, 2025). "A recent study shows that IL-1β–producing TAMs can be elicited by prostaglandin E2 and TNF-α presented in the tumor microenvironment." (PMID 41243973, 2025). "Key cytokines such as interleukin-6 (IL-6), tumor necrosis factor-alpha (TNF-α), interleukin-1 beta (IL-1β), and interferon-gamma (IFN-γ) are critical mediators of tumor progression, immune tolerance, and therapy resistance." (PMID 41401147, 2025). "IL-1β will stimulate the secretion of IL-17 by CD4 + T cells, accelerating tumor progression and reducing the efficacy of 5-FU." (PMID 40404908, 2025). "LMNB2 overexpression attenuated the YY2 tumor suppressive effect, while blocking caspase‐1/GSDMD activation, IL‐1β levels, and cell death rate." (PMID 39903759, 2025). "The relative abundance of Fusobacterium nucleatum and the expression levels of cytokine genes (IL-1β, IL-6, IL-10, IL-17, TNF) were measured in tumor and adjacent normal tissues to assess their differential expression and potential associations." (PMID 41267807, 2025). "M1 macrophages exhibit a strong pro-inflammatory profile, secreting cytokines such as TNF-α, IL-1β, and IL-6, thereby activating additional immune cells, especially CD8+ T cells, and enhancing tumor immune surveillance." (PMID 40475760, 2025). "The uniform manifold approximation and projection (UMAP) diagram revealed that BAX, IL1B, and TNF were predominantly expressed in epithelial cells and macrophages in tumor tissues." (PMID 39744500, 2025). "By conducting these experiments in non-tumor-bearing mice, we specifically isolated immunological changes attributable to HDM and IL-1β, avoiding confounding effects from carcinogen-induced or oncogene-driven inflammation seen in cancer models." (PMID 41445736, 2025). "This enhanced infiltration was accompanied by upregulated expression of pro-inflammatory cytokines (IFN-γ and IL-1β) and downregulation of the NK cell suppressor TGF-β, indicating BRQ remodels the tumor microenvironment to support NK cell activity." (PMID 41144149, 2025).